INS (insulin)
Diseases named in the same sentence as INS in open-access papers (continued):
Sharing a sentence is not in itself a finding about the gene and the disease.
Insulin resistance (continued). "In the present study, we found individuals with CGI had the highest level of insulin resistance, while subjects with IGT had better insulin sensitivity than with IFG." (PMID 28199386, 2017). "EGCG mimics insulin actions and promotes nuclear efflux of FOXO1 in skeletal muscle, resulting in increase in insulin receptor (IR) sensitivity and decrease in insulin resistance." (PMID 28531120, 2017). "Secretion is suppressed by insulin, and low levels of SHBG are frequently observed in states of insulin resistance and have been studied as a potential predictor of the development of T2DM." (PMID 28279160, 2017). "Since insulin resistance is conventionally believed to be central to T2DM we called the two attractors as insulin sensitive and insulin resistant attractors." (PMID 28767672, 2017). "Fasting insulin, 2 h OGTT insulin, HOMA-IR and FIGR showed the best correlations while other measures of insulin resistance showed weaker relationships." (PMID 28754153, 2017). "Insulin resistance was estimated using the HOMA-IR, [HOMA-IR = insulin (μU/mL) × glucose (mmol/L)/22.5]42." (PMID 28931850, 2017). "For LDL, concentrations of both total LDL-P and small LDL-P were associated with greater BMI, waist circumference, abdominal visceral adiposity, homeostasis model assessment of insulin resistance [HOMA-IR], and fasting insulin (P < 0.05 for all)." (PMID 28187765, 2017). "The high BCAAs level in obese patients was observed and positively correlated with body mass, insulin resistance, HOMA-IR (fasting insulin) and glucose intolerance." (PMID 28991897, 2017). "Another key finding in the present study was the variation in insulin resistance according to APOE genotype and plasma total SFA; nutrient-gene interactions were observed for both HOMA-IR and insulin." (PMID 28740125, 2017). "While HOMA- IR showed only a trend towards reduced insulin resistance, ITT revealed greater insulin sensitivity compared to control." (PMID 28121620, 2017). "In a model system, decreased AMPK activity resulted in insulin resistance and activation of AMPK-enhanced insulin sensitivity." (PMID 28811612, 2017). "In addition, low levels of MF increase insulin resistance and decrease glucose metabolism, and several studies have attempted to establish a relationship between MF, adiponectin levels (or the expression of adiponectin receptors), and reduce in insulin function." (PMID 28296952, 2017). "As insulin resistance is the most important factor in the pathophysiology of MS and because hypertension is also a complication of MS, supplementation with piceatannol may be useful for metabolic health, particularly for improving insulin sensitivity in obese men." (PMID 29057795, 2017). "Insulin resistance parameters were also drastically modified by HFD, with significant increases in fasting glucose, fasting insulin, and HOMA values." (PMID 28395666, 2017). "To evaluate the effects of PDX on palmitate-induced insulin resistance, we investigated the effect of PDX on levels of insulin-stimulated Akt and IRS-1 phosphorylation and glucose uptake." (PMID 28469249, 2017). "Substituting meat protein for protein from other animal sources increased insulin and HOMA-IR (homeostasis model assessment of insulin resistance)." (PMID 29211027, 2017). "FABP4 is considered as an important substance concerning insulin resistance in T2DM, and for the release of compensatory insulin secretion." (PMID 28654680, 2017). "InsR and IRS1 are the key proteins of the insulin signal pathway, and inhibition of mouse InsR and IRS1 activity can lead to insulin resistance in mice." (PMID 28432282, 2017). "Tumor necrosis factor-α is a macrophage-derived inflammatory factor; it alters insulin signaling in cultured cells and in vivo, and it has been reported that chronic exposure of cells or whole animals to TNF-α induces insulin resistance." (PMID 28178209, 2017).
Insulin resistance (continued). "The insulin level and HOMA-IR exhibited similar trends, which verified insulin resistance initiated on day 20 in rats fed the high fat-sucrose diet." (PMID 28820447, 2017). "However, according to recent studies including our results, although patients with PWS may have relative insulin sensitivity, insulin resistance and obesity are considered the most important factors in the occurrence of T2DM through the destruction of β-cell function." (PMID 28854950, 2017). "Therefore, among Africans, even a small increase in insulin resistance could lead to a rapid increase in the amount of released insulin required to maintain normal glucose tolerance, which suggests that this particular subpopulation is more vulnerable to the development of type-2 diabetes." (PMID 28286536, 2017). "Increased blood levels of BCAAs positively correlate with insulin resistance and have been used as signature profiles for T2DM, insulin-resistant states of obesity and Huntington’s disease." (PMID 28626421, 2017). "If ROS production is the reason of insulin resistance in 1α(OH)ase-silenced hepatocytes, inhibition of ROS by NAC should restore insulin sensitivity." (PMID 28978056, 2017). "Fasted glucose, fasted insulin and HOMA index of insulin resistance were all within normal reference ranges for both groups of adults." (PMID 28291957, 2017). "PA–BSA combined with LPS treatment is known to be a common insulin-resistance inducer, so we choose PA–BSA plus LPS (PA–LPS) to stimulate HepG2 cells and induce the insulin-resistance model." (PMID 29096724, 2017). "Insulin resistance was evaluated via PI3K/Akt and MAPK/Erk signaling following insulin stimulation using Western blotting." (PMID 29267310, 2017). "To examine the effects of adipose ATRAP downregulation on insulin resistance, we performed a glucose tolerance test (GTT) and an insulin tolerance test (ITT), which reflect the glucose tolerance and insulin sensitivity, respectively." (PMID 28335584, 2017). "For glycometabolism indices, it was observed that fasting plasma glucose (FPG), fasting insulin (FINS) and homoeostasis model assessment of insulin resistance (HOMA-IR) were significantly higher in the model group compared with control group (P < 0.01)." (PMID 28349964, 2017). "Certain miRNAs targeting the molecules in the insulin signal transduction pathway are dysregulated in saturated fatty acid (SFA)-induced obesity, and these miRNAs contribute to the development of insulin resistance in the liver and skeletal muscle." (PMID 29124099, 2017). "Systemic IR was evaluated using the homeostasis model of insulin resistance (HOMA-IR) index, which is calculated as fasting serum glucose fasting × serum insulin/22.5." (PMID 28300221, 2017). "Consistent with serum insulin concentrations, HOMA-IR, an index of insulin resistance, was much higher in OVX-control rats than the positive-control." (PMID 29151980, 2017). "Thus, the present study was performed to investigate whether vaspin can act on IRS/PI3K/Akt insulin signaling pathway and NF-κB inflammatory signaling pathway to improve pancreatic β cell secretion function and insulin resistance, and reduce islet inflammation." (PMID 29240812, 2017). "Primary outcome measures are changes in homeostasis model assessment of insulin resistance (HOMA-IR) and improvement rate of HOMA-IR by oral glucose tolerance test (OGTT) and insulin releasing test (Ins)." (PMID 28274268, 2017). "Insulin indices as assessed by HOMA scores indicated marked reduction in beta cell function and insulin sensitivity as well as increased insulin resistance in GDM women at the time of diagnosis." (PMID 28766127, 2017). "We found significant elevation of insulin-stimulated phosphorylated Akt in the skeletal muscle of AE2-treated mice, suggesting that AE2 administration improves insulin resistance impeded by hSeP treatment." (PMID 29162828, 2017).
Insulin resistance (continued). "EGCG can reduce Ser307 phosphorylation of IRS-1 to attenuate insulin signaling blockade through 5’-AMP-activated protein kinase (AMPK) activation pathway, eventually leading to reduction of insulin resistance." (PMID 28531120, 2017). "In skeleton muscles, SIRT2 acts as a key component of a signaling network required to maintain the status of insulin resistance and down-regulation of SIRT2 improves insulin sensitivity." (PMID 27659520, 2017). "Here, we report increased FNDC5 and PGC‐1α protein in skeletal muscle and adipose in HF sedentary mice that exhibit increased bodyweight, fasting glucose, insulin, HOMA‐IR and cellular insulin resistance as measured by decreased Akt activation." (PMID 28676551, 2017). "Showing comparison of mean, standard deviation and p-value in experimental and control groups for fasting blood glucose level (FBGL), plasma insulin level (PIL), glycemic control (GC), and insulin resistance (IR) in T2DM." (PMID 28811774, 2017). "Considering that ANG II causes insulin resistance and glucose intolerance, in the present study, the low plasma TG and NEFA concentrations in the Los-treated mice may have resulted from AT1 receptor antagonism, a condition that can ameliorate insulin sensitivity." (PMID 28481921, 2017). "Homeostasis model assessment (HOMA) helps in the calculation of fasting insulin level (FINS) and insulin resistance (IR)." (PMID 28746192, 2017). "IPGTT and intraperitoneal insulin tolerance test (IPITT) of HFHG + AAV-shAtg7 mice showed severe glucose intolerance and insulin resistance compared with HFHG + AAV-GFP mice." (PMID 29180700, 2017). "Our GTT and plasma insulin results support that both HFCS- and SUC- feedings promote systemic insulin resistance." (PMID 28629187, 2017). "In these experiments, they observed decreased serum glucose, insulin and TAG levels, and less insulin resistance as calculated by HOMA-IR29." (PMID 28986580, 2017). "As these two parameters are hallmarks of hepatic insulin resistance, these results show that BAT itself and likely other tissues contribute to improved insulin sensitivity in BAT‐Mfn2‐KO mice." (PMID 28539390, 2017). "Activated JNK cascade contribute to obesity and insulin resistance by phosphorylation of the insulin receptor substrate, IRS-1 that attenuates insulin signaling." (PMID 28540288, 2017). "HOMA2 model was used to evaluate insulin resistance (HOMA2-IR), pancreatic beta cell reserve (HOMA2-%B), and insulin sensitivity (HOMA2-%S)." (PMID 29234478, 2017). "Finally, to assess the hypothesis that insulin resistance may be related to functional differences as large or larger than those related to BMI, we performed a group level analysis splitting the sample by median insulin HOMA-IR score." (PMID 28093279, 2017). "After surgery, reduced blood glucose, insulin, and glycosylated hemoglobin were noted in patients and there was also decreased resistance to insulin, based on the ELISA results of HOMA-IR (Homeostasis Model Assessment of Insulin Resistance)." (PMID 28316999, 2017). "Cells treated with STO-609, an inhibitor of CaMKKβ, showed decreased insulin signalling and AMPK phosphorylation induced by exogenous NaHS in the insulin resistance model." (PMID 29038536, 2017). "Inflammatory factors can interfere with insulin signaling pathway of IRS/PI3K/Akt, which is the main molecular mechanism of insulin resistance." (PMID 29240812, 2017). "The predefined outcomes included fasting blood glucose (FBG), fasting blood insulin (FBI), glycated haemoglobin (HbA1c), and homeostatic model assessment of insulin resistance (HOMA-IR)." (PMID 28985741, 2017). "Here, we found that hemin affects insulin signaling, and alleviates palmitate-induced insulin resistance in cultured primary hepatocytes and HFD-induced insulin resistance." (PMID 28933767, 2017). "The insulin sensitivity was evaluated as the level of Matsuda ISI, a standard figure for evaluating insulin resistance." (PMID 28913363, 2017).
Insulin resistance (continued). "Given that SAT represents 90% of total fat mass, it has potential to greatly affect systemic insulin resistance via secretion of cytokines or release of free fatty acids that circulate to muscle where 85% of IMGU, insulin-mediated glucose uptake occurs." (PMID 28151993, 2017). "As insulin resistance plays a critical role in development and progression of NAFLD, we checked the insulin sensitivity of rats induced by the high fat-sucrose diet." (PMID 28820447, 2017). "Improved hepatic insulin sensitivity was abolished when Chga-KO mice were treated with PST, implicating a positive correlation between PST and the development of insulin resistance." (PMID 28228748, 2017). "According to the predictive value of DAG-species for lipid metabolism and insulin resistance in liver and skeletal muscle, we determined DAG levels also as classifying parameter for lipid metabolism and insulin resistance in adipose tissue." (PMID 28885548, 2017). "In the presence of adipose tissue insulin resistance, FFA levels are high, despite of high levels of circulating insulin, because of resistance to the anti-lipolytic action of this hormone." (PMID 28585093, 2017). "A high-MUFA diet also showed an improvement in insulin resistance when compared to a high-SFA diet in mice, with significantly lower fasting glucose and insulin concentrations and attenuated insulin secretion, in response to glucose challenge." (PMID 29065507, 2017). "Moreover, dietary factors such as refined and high-glycemic-index carbohydrates are other threatening factors that may contribute to impaired insulin secretion and pancreatic β-cell function, and induced insulin resistance before pregnancy, and lead to GDM during pregnancy." (PMID 28257029, 2017). "Insulin resistance reduces the ability of the body to regulate blood glucose levels, which results in an increased PPGR despite increased insulin secretion." (PMID 26794239, 2016). "IRS-1 is an important factor in the insulin signaling pathway, and TNF-α diminishes insulin-induced tyrosine phosphorylation of IRS-1 during the process of insulin resistance." (PMID 27324794, 2016). "Therefore, the significantly increased insulin concentrations could be also partly attributable to the four-week red meat/refined grain diet high in refined grains, red and processed meat promoting insulin resistance." (PMID 27809219, 2016). "The KK-Ay control mice showed impaired insulin sensitivity with markedly higher blood glucose levels than the C57BL/6J mice, whereas 1βEPP alleviated the insulin resistance and decreased the blood glucose levels in the KK-Ay mice." (PMID 27152706, 2016). "Fasting serum insulin was increased by 41% (P = 0.08) and the homeostatic model assessment of insulin resistance was increased by 60% in HFD vs. LFD mice, indicating that mice fed the HFD had impaired insulin sensitivity compared with LFD mice." (PMID 27351281, 2016). "In our conditions, the main metabolic tissue apparently involved in the alteration of systemic insulin resistance and glucose intolerance in PHD1−/− mice on LFD appears to be the liver, where a very significant decrease in insulin signaling was evidenced." (PMID 27094951, 2016). "The significant reduction in the evening postprandial insulin response and HOMA-IR estimate of insulin resistance after a day’s exposure to low-carbohydrate meals, raises two questions about the contribution of daily carbohydrate load to this effect." (PMID 27798656, 2016). "FXR can regulate insulin resistance as recently demonstrated in NASH patients treated with OCA, which improves insulin sensitivity." (PMID 27657051, 2016). "TT treatment lowered blood glucose, triglyceride, total cholesterol, and insulin levels, ameliorated hyperglycemia and hyperlipidemia, and exhibited protection against HFD-induced insulin resistance." (PMID 27271603, 2016).
Insulin resistance (continued). "In order to simulate conditions of insulin resistance in our in vitro model, we incubated HGEC with insulin for 24 h (termed as prolonged insulin treatment) and examined components of the insulin signaling pathway." (PMID 27434075, 2016). "As determined by assessment of the insulin × glucose product, HOMA-IR and QUICKI, eNAMPT-Ab also ameliorated whole-body insulin resistance." (PMID 27541013, 2016). "The highest hemoglobin A1c (HbA1c), fasting plasma insulin (FPI), homeostasis model assessment-insulin resistance (HOMA-IR), maternal BMI, placental weight, and triglyceride levels occurred in the lowest fT4 quintile and in the highest fT3/fT4 ratio quintile." (PMID 26910563, 2016). "Authors of this study suggested that decreased insulin sensitivity is a consequence of elevated plasma levels of triglyceride-rich lipoproteins independently of plasma NEFA levels and suggested that postprandial lipaemia could be the cause of insulin resistance." (PMID 26808523, 2016). "At re-fed state, however, LFD-chicken had higher glucose and insulin levels compared with HFD-chickens, suggesting that the chickens fed with LFD are more prone to develop insulin resistance by DEX challenge, compared to the chickens fed with HFD." (PMID 27073616, 2016). "In addition to previous reports of the association of an imbalance in Zn and Cu levels with increased oxidative stress and inflammation, which impair insulin secretion and action, Zn deficiency may lower SOD1 activity in pancreatic islets, which has been shown to increase insulin resistance." (PMID 27895622, 2016). "In apparent conflict with data showing GSH depletion in obesity, insulin resistance and fatty liver, two models in which GSH synthesis is blocked feature leanness, hypermetabolism and insulin sensitivity." (PMID 27788147, 2016). "IHCL are significantly related to insulin resistance, but the regulation of IHCL is a complex interplay between quantitative and qualitative diet (i.e., fat, fructose, protein), insulin action, and probably physical exercise." (PMID 27649157, 2016). "The frequencies of IL-6-producing T cells were not correlated with the values of insulin resistance index HOMA-IR (homeostatic model assessment of insulin resistance), perhaps because HOMA-IR calculation includes fasting insulin levels." (PMID 26918832, 2016). "In the presence of adipose tissue insulin resistance, FFA levels are high, despite high levels of circulating insulin, because of the resistance to the anti-lipolytic action of this hormone." (PMID 27973438, 2016). "Asparteate aminotransferase (AST), immunoreactive insulin (IRI), and homeostasis model assessment-Insulin resistance (HOMA-IR) was higher than these in NASH patients (p = 0.014, p = 0.013, respectively)." (PMID 26883167, 2016). "Next, we analyzed the expression of known negative regulators (i.e., C/EBPβ, HDAC4 and PTEN) of insulin sensitivity and known inducers (i.e., SOCS1 and SOCS3) of insulin resistance." (PMID 27711113, 2016). "TNF-α is a major mediator of chronic inflammation and insulin resistance, and neutralization of TNF–α significantly improves insulin sensitivity." (PMID 27716232, 2016). "Insulin response to oral glucose challenge (insulin AUC) was higher in those with PCOS, confirming insulin resistance in this group." (PMID 26574952, 2016). "Biochemical analyses indicate that ModO and MO women had significantly higher levels of homeostatic model assessment 2-insulin resistance (HOMA2-IR), glucose, insulin, HbA1c, and triglycerides than the control group." (PMID 27669236, 2016). "Citrulline levels negatively correlated with BW, BMI, WC, VFA and SFA, insulin resistance (HOMA-IR), and insulin secretion (HOMA-β and II)." (PMID 26788116, 2016). "To evaluate the effect of obesogenic environment on insulin resistance development, we evaluated PTP1B expression and IRS1 and AKT phosphorylation after insulin injection (cava vein)." (PMID 27479001, 2016).